ADAM17 (ADAM metallopeptidase domain 17)
Diseases named in the same sentence as ADAM17 in open-access papers (continued):
Sharing a sentence is not in itself a finding about the gene and the disease.
myeloid leukemia (2 papers, 2016). A clonal proliferation of myeloid cells and their precursors in the bone marrow, peripheral blood, and spleen. "ADAM17 has also been suggested to interact with CD13 on the surface of myeloid leukemia cells." (PMID 27658265, 2016).
non-alcoholic steatohepatitis (2 papers, 2019 to 2023). "Consequently, restoration of TIMP3 expression in mouse models of non-alcoholic steatohepatitis (NASH) reduced ADAM17 activity and lowered fibrotic activity in the liver, suggesting that ADAM17 is essential for NASH pathology." (PMID 31601007, 2019). "Since TNF-alpha is upregulated in the progression of nonalcoholic fatty liver disease (NAFLD) to non-alcoholic steatohepatitis (NASH), it is interesting to speculate that regulating the TNF-alpha release by targeting ADAM17 could serve as a therapeutic strategy to reduce liver inflammation." (PMID 38139236, 2023).
periodontitis (2 papers, 2022 to 2026). An acute or chronic inflammatory process that affects the tissues that surround and support the teeth. "Another way in which IL‐23R isoforms can be formed is by transmembrane cleavage by a disintegrin and metalloprotease 10 and 17 (ADAM10 and ADAM17), of which ADAM17 has been found to be elevated in patients with periodontitis." (PMID 41536464, 2026). "Additionally, our group recently discovered that Sema4D expressed on osteoclasts is cleaved by tumor necrosis factor-alpha converting enzyme (TACE; also called ADAM17) (paper under review), which plays a relevant proinflammatory role in periodontitis." (PMID 35628440, 2022).
primary sclerosing cholangitis (2 papers, 2013 to 2021). "Hepatic expression of numerous cytokines and adhesion molecules are increased in cholestatic liver diseases including primary biliary cholangitis (PBC) and primary sclerosing cholangitis (PSC), however, the pathophysiological role of ADAM17 in regulating these conditions remains unknown." (PMID 35095853, 2021).
prion disease (2 papers, 2017 to 2020). A transmissible disease that is caused by a protein that is able to induce abnormal folding of normal cellular proteins, leading to characteristic spongiform brain changes, which are associated with neuronal loss without an inflammatory response. "Moreover, decreased ADAM17-mediated alpha-secretase activity was previously shown to promote disease progression in prion disease and AD and to increase accumulation of Aß and pathogenic prions." (PMID 29988083, 2020).
prostate tumors (2 papers, 2016 to 2024). "Here, we provide evidence that PTEN loss in prostate tumours upregulates the expression of ADAM17, thereby activating NOTCH signalling." (PMID 27941799, 2016). "Bioinformatics analysis also showed an inverse correlation between the gene expression levels of PTEN and ADAM17 in prostate tumours." (PMID 27941799, 2016).
rheumatic disease (2 papers, 2022 to 2025). "Further analysis of ADAM17's differential expression by rheumatic disease types revealed statistically significant expression in PM/DM and RA with ILD patients, but not in pSS with ILD patients." (PMID 40077919, 2025). "Soluble CD62L can arise either from the splice variant transcript, which is more prevalent in rheumatic diseases, or from the classical shedding of surface CD62L via ADAM17 during transendothelial migration." (PMID 35216350, 2022).
Testicular torsion (2 papers, 2023 to 2024). Testicular torsion is when the spermatic cord to a testicle twists, cutting off the blood supply. "Inhibition of ADAM17 has been proposed as a therapeutic strategy to mitigate the impact of testicular torsion." (PMID 39057081, 2024).
thyroid cancer (2 papers, 2011 to 2022). "Our data indicate that activated EGFR also cooperates in thyroid cancer cell lines with the ADAM17/TACE sheddase in promoting ALCAM shedding and soluble ALCAM release." (PMID 21364949, 2011). "We also specifically investigated whether ADAM17/TACE was responsible for shedding of ALCAM in thyroid cancer cells and we found the existence of a novel 60-kDa soluble form of ALCAM." (PMID 21364949, 2011).
tylosis (2 papers, 2015 to 2016). "As a consequence of increased ADAM17 activity, tylosis-derived keratinocytes show several features of “constitutive wound healing” in vitro, including rapid closure in scratch-wound assay, and upregulated shedding of ADAM17-dependent substrates such as EGFR-family ligands and TNFα." (PMID 26419362, 2015).
uremia (2 papers, 2021 to 2022). A clinical syndrome associated with the retention of renal waste products or uremic toxins in the blood. "In our in vivo study, after 14 weeks of the induction of 75% renal mass reduction and the development of mild uremia with increases in BUN, PTH and renal levels of ADAM17 (an enzyme that increases in kidney disease of all etiologies), no changes in serum Ca or P levels were observed." (PMID 35807767, 2022).
Acute hepatitis (1 paper, 2021). Acute hepatic injury resulting from inflammation typically accompanied by increased serum alanine transaminase activity. "Specifically, deletion of ADAM17 in myeloid cells completely prevented carbon tetrachloride-induced acute hepatitis, and attenuated endotoxin-induced elevations in circulating TNFα levels." (PMID 35095853, 2021).
adenovirus infection (1 paper, 2020). "Caspase-8 cleavage produces a 50-kDa intracellular fragment during cell apoptosis induced by IFN-γ or TNF-α, while cellular ADAM-17 can produce an 80-kDa extracellular fragment of DSG-2 during adenovirus infection." (PMID 32457708, 2020).
age (1 paper, 2020). A temporal measurement of the time period elapsed since an identifiable point in the life cycle of an organism. "We pursued this possibility by more detailed analysis of the adult ADAM17 mutant (ADAM17−/−) retina, a tissue widely used for studying age‐related degeneration of the nervous system." (PMID 32715522, 2020).
AIDS (1 paper, 2024). A syndrome resulting from the acquired deficiency of cellular immunity caused by the human immunodeficiency virus (HIV). "A serum ADAM17 cutoff value of 462 pg/mL was identified as a diagnostic marker for the patient's AIDS phase." (PMID 39717606, 2024). "ROC curve analysis revealed that the pre-treatment serum ADAM17 level in the untreated HIV group had moderate diagnostic accuracy for the AIDS stage (area under the curve: 0.703, p = 0.028)." (PMID 39717606, 2024). "Additionally, an evaluation of the diagnostic efficacy of serum ADAM17 levels for identifying the AIDS stage demonstrated a close association between serum ADAM17 levels and the stage of AIDS." (PMID 39717606, 2024).
allergic rhinitis (1 paper, 2025). Inflammation of the nasal mucous membranes caused by an IgE-mediated response to external allergens. "There was other evidence that ADAM10 and ADAM17 influenced allergic rhinitis, which are also transmembrane metalloproteases." (PMID 40761581, 2025).
ameloblastoma (1 paper, 2022). The most common odontogenic tumor, arising from the epithelial component of the embryonic tooth and usually affecting the molar-ramus region of the mandible or maxilla. "Lastly,the ameloblastoma cell lines AM-1 and AM-3 were incorporated into the 3D model.RANKL release was validated through TACE/ADAM17 activation chemically or throughhOB co-culture." (PMID 36582941, 2022).
amyloid (1 paper, 2021). "In AD brains, ADAM17-positive neurons often colocalize with amyloid plaques and are considered potential therapeutic targets for AD." (PMID 33807157, 2021).
Anxiety (1 paper, 2022). Intense feelings of nervousness, tension, or panic often arise in response to interpersonal stresses. "Moreover, ouabain activated TNF-α-converting enzyme/a disintegrin and metalloprotease 17 (TACE/ADAM17), decreased N-methyl-D-aspartate (NMDA) receptor subunit 2A (NR2A) expression, and induced anxiety-like behavior in both genotype animals, independent of the presence of TNFR1." (PMID 36428505, 2022).
anxiety disorder (1 paper, 2022). A category of psychiatric disorders which are characterized by anxious feelings or fear often accompanied by physical symptoms associated with anxiety. "We propose that obesogenic diets rich in saturated fatty acids promote TACE/ADAM17-mediated proteolytic cleavage of critical neurodevelopmental and neuroinflammatory processes, and consequently, lead to hippocampal synaptic/structural impairments implicated with anxiety disorders." (PMID 35220393, 2022).
arthropathy (1 paper, 2020). Any disorder of the joints. "This concept is further supported by the observation that mice lacking iRhom2 are protected from bone resorption in a mouse model of hemophilia arthropathy, as are mice lacking the ADAM17 substrate TNFα or mice treated with the TNF antagonist Etanercept." (PMID 33227998, 2020).
autoimmune thyroiditis (1 paper, 2025). "XYSJW may enhance the synthesis of the target protein ADAM17 by suppressing miR-326 expression in the thyroid tissue of rats with experimental autoimmune thyroiditis, hence hindering Th17 cell development and diminishing IL-17 mRNA expression (Li YN." (PMID 40584613, 2025).
bladder tumor (1 paper, 2021). "Moreover, we found that the absence of PD-L1 was associated with strong expression of ADAM17 and, although less pronounced, with expression of ADAM10 within both bladder tumor regions." (PMID 33672843, 2021).
CADASIL (1 paper, 2016). "Collectively, these findings support the concept that the diminished myogenic tone and CBF deficits in CADASIL are caused by TIMP3-mediated suppression of the ADAM17/HB-EGF/(ErbB1/ErbB4) pathway." (PMID 27476853, 2016).
calcification (1 paper, 2019). Process by which organic tissue becomes hardened by the physiologic deposit of calcium salts. "Thus, dietary Bβglucans inhibit leukocyte superoxide production and leukocyte, renal and aortic ADAM17- and nSMase2 gene expression attenuating systemic inflammation in health, and renal injury and aortic calcification despite hyperphosphatemia in CKD." (PMID 31780737, 2019).
central obesity (1 paper, 2024). "Impaired clearance of dead cells and debris in central obesity led to their accumulation, which activated immune cells and induced cytokine regulators such as ADAM17 to increase the inflammatory milieu." (PMID 38550672, 2024). "The increased effect of ADAM17 in central obesity is related to a decrease in the expression of the tissue inhibitor metalloproteinase 3 (TIMP3)." (PMID 38550672, 2024). "Thus, we conclude that PS, ADAM17, and sMER play an important role in efferocytosis activity in central obesity." (PMID 38550672, 2024).
Cholestatic liver disease (1 paper, 2021). "To evaluate for potential applicability of our findings in the clinical setting, we characterized cholestatic liver disease-related changes in ADAM17 protein expression in liver biopsies obtained from patients with PBC and PSC." (PMID 35095853, 2021). "Although a number of studies have highlighted ADAM17 activity as an important regulator of liver injury and repair, the role of ADAM17 in the context of cholestatic liver disease is poorly understood." (PMID 35095853, 2021). "Current findings therefore suggest that ADAM17 may regulate the initiation/progression of liver injury in cholestatic liver disease, as well as the development of cholestatic liver disease-associated sickness behavior development." (PMID 35095853, 2021). "Whether concurrent inhibition of MMP-1 and MMP-13 can act synergistically with ADAM17 remains uncharacterized in cholestatic liver disease." (PMID 35095853, 2021).
chronic bronchitis (1 paper, 2024). A type of chronic obstructive pulmonary disease characterized by chronic inflammation in the bronchial tree that results in edema, mucus production, obstruction, and reduced airflow to and from the lung alveoli. "ADAM17 upregulation followed by SIRT1 suppression can lead to decreased ciliation, mucus hypersecretion, and attenuated MCC, a hallmark of chronic bronchitis in smokers and COPD." (PMID 39682757, 2024).
chronic lung disease (1 paper, 2018). According to the definitions of the American and British Thoracic Societies, including pulmonary functional tests, X-rays, and CT scans for items such as fibrosis, bronchiectasis, bullae, emphysema, nodular or lymphomatous abnormalities. "Here, we review evidence suggesting that hyperactivity of the EGFR/ADAM17 axis plays a role in the development of chronic lung disease in both CF and COPD." (PMID 29540993, 2018). "In this review, we focus on a signaling pathway called the EGFR/ADAM17 axis and its potential role in chronic lung disease, in particular CF and COPD." (PMID 29540993, 2018). "So far, polymorphisms associated with the ADAM17, AREG, or EGFR genes have not been directly linked to chronic lung disease, but that may be due to limitations of the studies." (PMID 29540993, 2018).
Chronic Obstructive Asthma (1 paper, 2024). Chronic airway obstruction caused by asthma. "Our data support prior work that has shown that ADAM17 upregulation in primary bronchial fibroblast and bronchial biopsies from chronic obstructive asthma patients accelerates subepithelial fibrosis by enhancing extra cellular matrix production and fibroblast differentiation." (PMID 39682757, 2024).
chronic pancreatitis (1 paper, 2023). A chronic inflammatory process causing damage and fibrosis of the pancreatic parenchyma. "constructed a model of chronic pancreatitis using Adam17ex/ex mice (which are homozygous Adam17ex alleles that result in a significant decrease in ADAM17 expression) and their wild-type (WT) homogeneous mice." (PMID 36969002, 2023).
deep vein thrombosis (1 paper, 2017). "However, the Incyte inhibitor, INCB7839, that targets ADAM10 and ADAM17 and thus almost all shedding events, was in phase II clinical trials where deep vein thrombosis was the only reported side effect." (PMID 29230082, 2017).
dementia (1 paper, 2019). Loss of intellectual abilities interfering with an individual's social and occupational functions. "Several of the connections we found in our network analysis, such as GSK3B, MAPT, ADAM17, and PSEN1 are also involved in other dementias than AD." (PMID 31797941, 2019).
dissection (1 paper, 2022). The separation and isolation of tissues for surgical purposes, or for the analysis or study of their structures. "Reprogrammed macrophages exaggerated vascular inflammation through the HIF1α-ADAM17 pathway and excessive ROS production, ultimately leading to aortic dissection." (PMID 35211530, 2022).
Ebola (1 paper, 2020). "ADAM-17 regulates IL-6 class switching as a mediator between pro- and anti-inflammatory responses to viral antigenic stimuli in Ebola, SARS-CoV and dengue infections in humans." (PMID 32256705, 2020).
endometrioid ovarian cancer (1 paper, 2021). "Nevertheless, investigation of ADAM17 as a tumor marker in a larger subgroup of endometrioid ovarian cancer would be of interest." (PMID 34771725, 2021).
fungal infection (1 paper, 2020). "In addition to ADAM10, ADAM17 which is also known as tumor necrosis factor-α converting enzyme (TACE) may play a divergent role during the different phases of bacterial, viral, and fungal infection." (PMID 33392273, 2020).
gastric adenocarcinoma (1 paper, 2022). "One available study showed high levels of ADAM10 and ADAM17 transcripts in gastric adenocarcinoma." (PMID 36286024, 2022).
glomerular diseases (1 paper, 2025). "usCD163 has been demonstrated to reflect renal CD163-M in glomerular diseases, as it is enzymatically cleaved by the inflammation-responsive protease ADAM17." (PMID 40052170, 2025).
Hashimoto thyroiditis (1 paper, 2021). An autoimmune disorder caused by the production of autoantibodies against thyroid tissue. "Our previous study also confirmed that elevated miR-326 levels regulate the IL-23/IL-23R/Th17 cell axis by targeting a disintegrin and metalloprotease 17 (ADAM17) in Hashimoto’s thyroiditis." (PMID 34140947, 2021).
HCMV infection (1 paper, 2023). "Alterations in both cell surface and soluble TNFR2 induced by HCMV infection were therefore consequent to the targeting of ADAM17 by UL148 and UL148D." (PMID 37561786, 2023). "Regulation of TNFα-induced cytokine responses and NK inhibition during HCMV infection were dependent on this impairment of ADAM17." (PMID 37561786, 2023). "The initial aim of this study was to investigate the regulation of TNFR2 during HCMV infection; however, this led to the finding that its altered levels were an indirect consequence of the targeting of A Disintegrin And Metalloproteinase 17 (ADAM17)." (PMID 37561786, 2023). "Taken together, these data suggest that the lack of surface ADAM17 expression during wild-type HCMV infection is not caused by degradation of its mature form, but retention and absence of processing of its immature form inside the cell." (PMID 37561786, 2023). "We thus describe the identification of two viral genes responsible for down-regulating ADAM17, detailing the profound effect this has on the cell-surface proteome and defining some of the important immunological consequences of this in the context of HCMV infection." (PMID 37561786, 2023). "In exploring the finding that HCMV infection up-regulates tumor necrosis factor receptor 2 (TNFR2), a ligand for the pro-inflammatory antiviral cytokine TNFα, we found that the underlying mechanism was due to targeting of the protease, A Disintegrin And Metalloproteinase 17 (ADAM17)." (PMID 37561786, 2023). "Using P < 0.05 as a cutoff, the total number of ADAM17 substrates stabilized by wild-type HCMV infection numbered 114, one hundred and one of which have not previously been reported to be cleaved by ADAM17." (PMID 37561786, 2023). "UL148 and UL148D achieved this through their targeting of ADAM17, expression of a functionally active cell-surface version of which was markedly up-regulated during HCMV infection in the absence of the two genes." (PMID 37561786, 2023). "This mature form was absent in Merlin-infected cells, indicating that ADAM17 processing had been impaired during wild-type HCMV infection." (PMID 37561786, 2023).
Hyperammonemia (1 paper, 2020). An increased concentration of ammonia in the blood. "Hyperammonemia reduces ADAM17 in the membrane, reducing TNFR1 shedding and resulting in increased TNFR1 in the membrane." (PMID 32917219, 2020). "We therefore assessed the effects of hyperammonemia and of strychnine on membrane expression of ADAM17." (PMID 32917219, 2020). "It is now shown that increased membrane expression of TNFR1 in hyperammonemia would be due to enhanced glycinergic neurotransmission and reduced membrane expression of ADAM17." (PMID 32917219, 2020). "This suggests that hyperammonemia could increase TNFR1 membrane expression by reducing its shedding mediated by ADAM17." (PMID 32917219, 2020). "Hyperammonemia reduces the phosphorylation at Tyr204 of Erk to 65 ± 9%, increases the phosphorylation at Thr180/Tyr182 of p38 to 142 ± 9%, and the phosphorylation at Thr735 of ADAM17 to 137 ± 11%, of control rats, and these effects are not reversed by strychnine." (PMID 32917219, 2020). "Hyperammonemia reduces ADAM17 in the membrane by increasing PKC activity, as supported by the fact that inhibition of PKC normalizes the levels in the membrane of both ADAM17 and TNFR1." (PMID 32917219, 2020). "However, the results reported here show that this mechanism is not responsible for the effects of hyperammonemia on ADAM17." (PMID 32917219, 2020).
Hyperkalemia (1 paper, 2024). An abnormally increased potassium concentration in the blood. "The combined intervention including ADAM17 knockdown and eplerenone treatment provided an additional cardioprotective effect compared with that produced by monotherapy and produced no side effects, such as hyperkalemia, which was a crucial finding in the search for new treatments for DCM." (PMID 38799171, 2024).